BCL2 (BCL2 apoptosis regulator)
Diseases named in the same sentence as BCL2 in open-access papers (continued):
Sharing a sentence is not in itself a finding about the gene and the disease.
liver fibrosis (63 papers, 2015 to 2025). "We observed that TAA-induced liver fibrosis was associated with increased pro-apoptotic protein expression (Bax and caspase-3), in addition to a decrease in anti-apoptotic protein expression (Bcl-2)." (PMID 40520202, 2025). "The interference of BCL-2 associated apoptotic signaling pathway in hepatocyte can affect hepatocyte function, inflammatory response, and hepatic fibrosis." (PMID 32710621, 2020). "The reduced activity of NF-κB decreases the levels of Bcl-2, an anti-apoptotic protein, facilitating the elimination of activated liver stellate cells, key elements in the progression of liver fibrosis." (PMID 40332363, 2025). "In a preclinical study of a mouse model of liver fibrosis induced by CCl4, exosomes containing miR–181–5p were shown to increase autophagy and decrease liver fibrosis caused by TGF-β1 by blocking the STAT3/Bcl-2/Beclin 1 pathway in HSCs." (PMID 41244150, 2025). "The Bcl-2/Bax ratio—a key indicator for assessing apoptotic propensity —has been validated in liver fibrosis models, where tannic acid A inhibits hepatocyte apoptosis by elevating this ratio." (PMID 41154766, 2025). "The NF-κB pathway involved in the progression of liver fibrosis by activating and transcribing genes such as BCL2 and IL-1, which allow aHSCs to survive and maintain qHSC activation." (PMID 38461449, 2024). "The presence of exosomes containing miR-181-5p has been found to promote autophagy in liver fibrosis by inhibiting the STAT3/Bcl-2/Beclin1 pathway, resulting in reduced liver fibrosis." (PMID 39095888, 2024). "Wogonin significantly increased the Bax/Bcl-2 ratio in T6 cells and regulated the activation and apoptosis of hepatic stellate cells to reduce liver fibrosis." (PMID 35893891, 2022). "Preconditioning of MSCs with MT showed lower expressions of TGF-β1 and Bax and lowered ALT content but higher expressions of MMPs and Bcl2 with the MSCs group in the treatment of liver fibrosis." (PMID 35663940, 2022). "We measured the expressions of Bax, Bcl-2, Caspase 3, and Caspase 9, which are all involved in apoptosis, to determine the anti-apoptotic activities of geniposide in CCl4-induced liver fibrosis." (PMID 34899328, 2021). "In this study, DHM inhibited Bax expression while promoted Bcl-2 expression in TAA-induced liver fibrosis in mice." (PMID 34867416, 2021). "Hesperidin and naringenin in CRP affect the apoptosis pathway by acting on CASP3, BAX, and BCL2, reducing the likelihood of liver fibrosis." (PMID 33912040, 2021). "Qu et al73 found that exosomes containing miR‐181‐5p increased autophagy and alleviated TGF‐β 1‐induced liver fibrosis by inhibiting the STAT3/Bcl‐2/Beclin‐1 pathway in HST cells and CCl4‐induced liver fibrosis in mice." (PMID 33506641, 2021). "The results showed that the expression of cleaved caspase‐3 was increased and that the Bax/Bcl‐2 ratio was enhanced in HSCs from CCl4‐induced liver fibrosis mice injected with AAV‐shPLK1 compared with the AAV‐empty group." (PMID 32463161, 2020). "A study suggested that puerarin at doses of 40–80 mg/kg significantly increased the activated HSCs apoptosis and downregulated Bcl-2 expression in a CCl4-induced liver fibrosis model." (PMID 33082829, 2020). "BCL2, an apoptosis regulator localized to the outer mitochondrial membrane, plays an important role in liver fibrosis." (PMID 32650615, 2020). "Consistent with the histological evidence, Venetoclax also reduced the hydroxyproline content in the miR-122 KO livers by ~50%, underscoring the significance of BCL2 in mediating liver fibrosis and the therapeutic efficacy of Venetoclax in vivo." (PMID 32650615, 2020). "In our study, high expression levels of the antiapoptotic gene bcl-2 were observed in cells treated with P. barbatus, which can facilitate the progression of hepatic fibrosis." (PMID 31438947, 2019).
liver fibrosis (continued). "Our result showed that AG can significantly accelerate TGF-β1-induced apoptosis of HSC, possibly by upregulating Bax expression and downregulating Bcl-2 expression, thus providing a pro-apoptosis strategy against liver fibrosis." (PMID 28481234, 2017). "Individuals with higher scores of liver fibrosis (i.e. F3-F4 scores) produced significantly less Bcl-2 in response to IL-7 (10ng/ml) compared to those with lower degrees of fibrosis (i.e. F0-F2) (p = 0.02, unpaired Student’s t-test)." (PMID 27315061, 2016). "We show that forced expression of Bcl2 in liver disrupts BA homeostasis leading to severe cholestatic liver fibrosis, which is accompanied by the drastic induction of H19." (PMID 26838806, 2016). "Further studies are necessary to dissect out cell type specific roles of Bcl2 and H19 in liver fibrosis and other chronic liver diseases." (PMID 26838806, 2016). "Immunohistochemistry (IHC) staining revealed a strong induction of BCL2 protein in liver fibrosis, NASH, alcohol and HCV cirrhosis relative to normal livers." (PMID 26838806, 2016). "HSCs overexpress BCL2 during liver fibrosis, contributing to their resistance to apoptosis." (PMID 41196648, 2025). "Furthermore, Bcl-2 depletion was found to play a significant role in the development of liver fibrosis, as activated HSCs are resistant to most proapoptotic stimuli due to high Bcl-2 expression." (PMID 37397479, 2023). "Recent studies have found that metformin can improve liver function and hepatic fibrosis induced by NASH by upregulating BIM, BAD and PUMA and downregulating Bcl-2 and Bcl-xL to induce apoptosis in HSCs, which provides a new approach for the management of hepatic fibrosis." (PMID 38086792, 2023). "Results indicated that melatonin administration was able to decrease positive apoptotic cells, Bax expression, and cleaved caspase‐3/caspase‐3 ratio, and induce higher levels of the antiapoptotic protein Bcl‐2, using different animal models with CCl4‐derived liver fibrosis." (PMID 35404472, 2022). "In vitro experiments suggested that the mechanism may involve hesperidin and naringenin acting on CASP3, BAX, and BCL2 to affect the apoptosis pathway, attenuating liver fibrosis." (PMID 33912040, 2021). "Further, overexpression BCL2 in mice livers resulted in cholestatic liver fibrosis, indicating that BCL2 might be a pro-fibrogenic factor in the liver." (PMID 32650615, 2020). "Thus, it is reasonable to use Venetoclax as a tool to verify the mechanistic role and to test the therapeutic value of targeting BCL2 for liver fibrosis." (PMID 32650615, 2020). "In a rat model of hepatic fibrosis and mouse hepatic stellate cells, ADSC-Exos could activate cell autophagy and reduce TGF-β1-induced hepatic fibrosis via suppressing the STAT3/Bcl-2/Beclin1 pathway." (PMID 31391108, 2019). "Primary rat HSCs derived by carbon tetrachloride (CCl4)-induced hepatic fibrosis model showed increasing Bcl-2 levels and lower expression of caspase-9 compared to normal controls, supporting their pro-apoptotic role in HSCs via targeting Bcl-2 and members of caspase signaling." (PMID 30544653, 2018). "HNP-1 secreted by neutrophils may exacerbate alcohol-induced hepatic fibrosis and hepatocyte apoptosis with a decrease in Bcl2 expression and an increase in miR-34a-5p expression." (PMID 28403148, 2017). "This study is potentially significant because it may allow us to explore BCl2 as a promising drug target for liver fibrosis and cirrhosis." (PMID 26838806, 2016). "We further confirmed the elevation of BCL2 protein levels in nonalcoholic steatohepatitis (NASH), alcohol and HCV cirrhosis by Western blot.These results demonstrated a positive correlation of activation of BCL2 and H19 with the development of liver fibrosis and cirrhosis in both humans and mice." (PMID 26838806, 2016).
liver fibrosis (continued). "Notably, its administration mitigated the progression of radiation-induced liver fibrosis, likely through the modulation of key apoptotic signaling pathways, such as the Bax/Bcl-2 axis, and the reduction in oxidative stress markers, including superoxide dismutase (SOD) and malondialdehyde (MDA)." (PMID 39457507, 2024). "In addition, during hepatic oxidative stress, curcumin inhibits the mitochondrial translocation and subsequent intrinsic mitochondrial apoptotic pathway of Bax, thereby preventing Bax-mediated Bcl2 inactivation and inhibiting the development of hepatic fibrosis." (PMID 38313314, 2024). "Network pharmacology analysis identified BCL2, CASP3, and CASP8 as major targets of β-sitosterol in liver fibrosis management." (PMID 38461449, 2024). "Quercetin, known for its strong antioxidant and anti-inflammatory properties, has been found to inhibit HSCs activation by affecting the NF-κB/MAPK and Bcl-2/BAX pathways, thereby delaying the progression of liver fibrosis." (PMID 39185304, 2024). "Inhibition of BCL2 functions using Venetoclax suppressed human HSC-derived cells (LX-2) from transforming into pro-fibrogenic status and inhibited liver fibrosis that developed in the miR-122 KO mice." (PMID 32650615, 2020). "Myeloid cell leukemia-1 (MCL-1), a member of the B-cell CLL/Lymphoma 2 (BCL-2) apoptosis family, is involved in liver fibrosis and is targeted by miR-29b via its 3’-UTR in cultured cell lines." (PMID 28190086, 2017). "We have demonstrated that exosomes containing miR‐181‐5p can increase autophagy and reduce TGF‐β1‐induced liver fibrosis by inhibiting the STAT3/Bcl‐2/Beclin 1 pathway in HST cells and a CCl4‐induced liver fibrosis mouse model." (PMID 28382720, 2017). "Production of Bcl-2 following IL-7 stimulation was also lower in HCV infection and inversely related to the degree of liver fibrosis." (PMID 27315061, 2016). "In contrast, aged mice exhibited hepatic fibrosis, with increased collagen deposition and upregulation of genes related to fibrosis (Acta2, MMP2, TGF-ß1, and Col1a2), cirrhosis (CXCR4, SOX9, DCN, and MFAP4), and cancer (Bcl2, CDKN2a, c-Myc, and Fn1)." (PMID 39851554, 2025). "At the liver fibrosis stage, it hindered stromal ECM deposition, modifying TGF-1β, endoplasmic reticulum stress (ERs), and apoptosis via regulation of NF-кB/IкBα, p38-MAPK, and Bcl-2/Bax signaling." (PMID 40892759, 2025). "Furthermore, we examined the relative mRNA expression levels of key markers related to hepatic fibrosis (Acta2, Cola2, TGF-β1, and MMP2), cirrhosis (CXCR4, SOX9, DCN, and MFAP4), and cancer (Bcl2, CDKN2a, c-Myc, and Fn1) across the experimental groups." (PMID 39851554, 2025). "The effects of curcumin on hepatic fibrosis rats or mice models mainly include three aspects: The indicators related to liver cell structure and function mainly include ALT, AST, ALP, ALB, A/G, TBIL, bax protein, bcl-2 protein and index of liver." (PMID 38781262, 2024). "Compared with the alcohol group, ADAM8 mRNA and protein expression, cell viability, and the expression of liver fibrosis markers and MAPK signaling pathway-related factors (p-ERK1/2, PCNA, Bcl-2, p-c-Jun, TGFβ1, p–p38 MAPK and HSP27) reduced significantly in the si-ADAM8-2 group." (PMID 39407108, 2024). "Previous studies have reported that G. biloba extract can prevent renal fibrosis by modulating Akt/mTOR signaling in diabetic nephropathy; it can also reduce the occurrence of liver fibrosis through NF-κB and TGF-β1 or by regulating p38 MAPK, NF-κB, and Bcl-2/Bax signaling to relieve liver fibrosis." (PMID 35707278, 2022).
liver fibrosis (continued). "Among six potential transcription factors (conserved between mice and humans) that bind at the proximal promoter region of the identified BCL2 gene, we focused on c-MYC as it is known to modulate liver fibrosis and is regulated by miR-122 through E2F1 and TFDP2 in mouse hepatic cells." (PMID 32650615, 2020). "In addition, it has been reported that Asiatic acid can ameliorate CCl4-induced liver fibrosis in rats by regulating PI3K/AKT/mTOR, Bcl-2/Bax, Nrf2/ARE, NF-κB/IκBα and JAK1/STAT3 signaling pathways." (PMID 31467589, 2019). "In hepatic fibrosis animal models, estradiol treatment markedly suppressed early apoptosis and hepatic fibrosis, reduced collagen content and α-SMA expression, and induced Bcl-2 expression." (PMID 31362375, 2019). "Additionally, in studies of liver fibrosis, a correlation has been seen between the levels of TIMP-1 and Bcl-2." (PMID 26366732, 2015). "However, the effects of curcumin on bcl-2 protein, IL-6 in hepatic fibrosis models and index of liver in mice were not statistically significant." (PMID 38781262, 2024). "However, the effect of curcumin on bcl-2 protein in the hepatic fibrosis models was not statistically significant." (PMID 38781262, 2024). "However, the effects of curcumin on bcl-2 protein, IL-6, and mice index of liver in the hepatic fibrosis models were not statistically significant." (PMID 38781262, 2024). "Furthermore, the strong negative correlation between Bcl-2 protein expression and collagen deposition in the liver supports an interaction between liver fibrosis and apoptosis." (PMID 34663892, 2022). "Quercetin at doses of 5–200 mg/kg significantly alleviated liver fibrosis induced by CCl4 through regulating inflammation involving NF-кB and MAPK signals and protecting from apoptosis via inhibiting proapoptotic gene Bax and improving antiapoptotic gene Bcl-2 expression." (PMID 33082829, 2020). "Studies in rodents have demonstrated that apoptosis in HSCs with an along with an increase in caspase 3 activity or a reduction in Bcl-2/Bax ratio, could promote the regression of CCl4 and BDL-mediated liver fibrosis, suggesting a potential role of apoptosis of HSCs in attenuating the disease." (PMID 27489164, 2016). "TC improved Bcl2/Bax ratio, decreased apoptosis, CYP2E1 protein expression and liver fibrosis levels, however, EV offered no such protection." (PMID 29371918, 2017).
viral infection (62 papers, 2005 to 2025). "Here we review the structural biology, interactions, and mechanisms of action of virus-encoded Bcl-2 proteins, and how they impact on host-virus interactions to ultimately enable successful establishment and propagation of viral infections." (PMID 28984827, 2017). "It is becoming apparent for the best understood virus-encoded Bcl-2 proteins that, in contrast to mammalian apoptosis, multiple mechanisms of action exist, though many of these need to be clarified with quantitative structure and binding studies that are complemented by live viral infection models." (PMID 28984827, 2017). "In response to RNA viruses, pDC-A showed increased Bcl2-dependent survival and superior IFN-I responses, but was susceptible to virus infection." (PMID 41087726, 2025). "The regulation of cellular apoptosis is critical to many aspects of viral infection, and assimilated viral Bcl-2 genes frequently mimic the activity of pro-survival cellular Bcl-2 genes while avoiding the regulation directed at the cellular proteins." (PMID 38932171, 2024). "Like other gammaherpesvirus genomes, γHV68 contains a Bcl-2 homolog, M11 (or viral Bcl-2, vBcl-2), and inhibits apoptosis induced by a number of stimuli, including viral infection." (PMID 38932171, 2024). "The ability of viruses to manipulate cellular death induction through apoptosis and autophagy by the expression of viral pro-survival Bcl-2 proteins provides the prospect of targeting this family in viral disease." (PMID 38932171, 2024). "During virus infection, the downregulation of Bcl‐2 (26 kDa), accompanied by an increase in Bax (21 kDa), which led to an increase in Bax/Bcl‐2 ratio, was detected from 12 to 36 h.p.i." (PMID 37843231, 2023). "Considering that viral infection promotes the degradation of BCL2, we examined which protein is involved in this process." (PMID 36928081, 2023). "BCL-2 is a key modulator of cellular lifespan and has been shown to be modulated by pathogen/host interactions and by certain cytokines downstream of viral infection and/or tumor microenvironment." (PMID 36569952, 2022). "The Western blot assay confirmed Bcl2 overexpression after viral infection, and DMSO and empty vector treatments were used as the controls." (PMID 35563442, 2022). "NFkB is activated during many viral infections and mediates anti-apoptotic effects by inducing the expression of anti-apoptotic genes, including BCL-2." (PMID 32032391, 2020). "The expression of cleaved PARP and cleaved Caspase-3 was increased by A/WSN/1933 virus infection in a time-dependent manner, while the expression of anti-apoptotic Bcl-2 was decreased." (PMID 31191534, 2019). "All these results indicate that during PR8 viral infection, females activate transcriptional processes to maintain high levels of Bcl-2 protein." (PMID 30105026, 2018). "The enhancement of virus-induced apoptosis in macrophages by ABT-737 confirms a pro-survival role of Bcl-XL (and perhaps Bcl-2) during viral infection." (PMID 27537523, 2016). "Bcl2 can suppress cell death induced by a variety of stress applications including growth factor withdrawal, chemotherapy, irradiation, and viral infection." (PMID 24967145, 2014). "The combination of activation and proliferation markers (CD38, HLA-DR, Ki-67 and Bcl-2) expressed by CD8 T cells have been recently proposed to identify the whole population of virus-specific effector CD8 T cells induced by viral infection." (PMID 20808900, 2010). "BCL-2 serves as an important regulator of cellular longevity and is influenced by interactions between pathogens and hosts, as well as by specific cytokines that are activated following viral infection." (PMID 40867920, 2025).